FAP (fibroblast activation protein alpha)
Diseases named in the same sentence as FAP in open-access papers (continued):
Sharing a sentence is not in itself a finding about the gene and the disease.
tumor (continued). "Tumor-cell-specific FAP expression characterized an epithelial-to-mesenchymal transition (EMT)-like state and was spatially associated with profound immunosuppression, marked by enrichment of regulatory T cells, exhausted CD8+ T cells, and M2-like macrophages, particularly at the invasive border." (PMID 41608569, 2026). "This design integrates two key functions: FAP-specific targeting and acid-triggered MnO2 nanoprobes releasing Mn2+ for T1-weighted MR contrast enhancement; Cy7 fluorescence increase achieving tumor-to-background ratio in NIRF imaging." (PMID 42006731, 2026). "Targeting surface markers such as FAP can selectively deplete tumor-promoting CAFs." (PMID 41590379, 2026). "CONCLUSIONS: Our findings suggest that CAFs constitute a relatively small cell population in subcutaneously transplanted tumor models, and that fractionated radiotherapy may induce a moderate increase in FAP+ cells in LLC tumors." (PMID 41761350, 2026). "Additionally, fibroblast differentiation, extracellular matrix (ECM) remodeling, and also tumor invasion and migration are attributed to FAP." (PMID 40694103, 2026). "More studies are needed to validate this hypothesis and clinical significance of FAP imaging, and correlation between FAP positivity (and/or FAP positive cCAFs) with tumor aggressiveness and invasiveness." (PMID 38634185, 2025). "In conclusion, FAP+ fibroblasts could motivate the proliferation and tumor angiogenesis characteristics SPP1+macrophages." (PMID 40438108, 2025). "Furthermore, the study demonstrated that the injection of DCs that had been transduced with FAPα mRNA led to the direct inhibition of tumor growth." (PMID 40918451, 2025). "In a transgenic mouse model, depletion of FAP-expressing cells led to rapid hypoxic necrosis mediated by interferon-gamma (IFN-γ) and tumour necrosis factor-alpha (TNF-α), both associated with CD8+ T cell-dependent tumour cell killing." (PMID 39780187, 2025). "This selectivity is crucial for their in vivo applicability, as recognition of these enzymes by FAP-radiotracers could compromise tumor selectivity and reduce overall in vivo performance." (PMID 40000459, 2025). "Furthermore, TGF-β1-activated CAFs promote tumor progression by modulating metabolic processes, such as autophagy, and specific molecules like FAP-α, potentially impacting ferroptosis pathways." (PMID 40416987, 2025). "Induced cross-reactive antibodies that targeted both tumor and stromal FAPα+ cells." (PMID 40918451, 2025). "Due to its selective expression in CAFs, minimal presence in normal tissue, and critical role in tumor progression, FAP has emerged as a promising clinical target, driving the development of novel strategies for imaging, radioligand therapy, and targeted drug delivery." (PMID 41441395, 2025). "Together, these studies highlight the early but growing evidence that FAP-targeted theranostics may offer a safe, tolerable, and effective therapeutic option across multiple tumor types, particularly in settings where conventional treatments have failed." (PMID 41441395, 2025). "These FAPα+CD144+ endoCAFs acquire vasculogenic mimicry(VM)capabilities to facilitate metastasis while promoting in situ tumor proliferation and invasion via the CD144-β-catenin-signal transducer and STAT3 signaling axis, exerting dual pro-tumorigenic functions." (PMID 40861469, 2025). "Because FAP-targeted radiopharmaceuticals are rapidly cleared via the kidneys and exhibit low uptake in normal tissues, FAP PET provides a higher tumor-to-background ratio (TBR) and reduced physiologic uptake in organs such as the brain and liver, compared to FDG PET." (PMID 40805245, 2025). "FAP inhibition may initially accelerate tumor growth, creating a larger, but less invasive tumor that is more accessible for surgical removal." (PMID 41233863, 2025).
tumor (continued). "In addition, several studies explored targeted delivery of radioisotopes or drugs to tumours by using anti-FAP antibodies, resulting in therapeutic regressions in preclinical cancer models." (PMID 39780187, 2025). "Furthermore, the exosome-like nanovesicles (eNVs)-FAP vaccines derived from FAP gene-engineered tumor cells have also demonstrated promising antitumor potential in preclinical studies." (PMID 40890855, 2025). "FAP also contributes to various pro-tumorigenic processes, including resistance to chemotherapy, induction of angiogenesis, immunomodulation, and extracellular matrix modification, all of which support tumor progression." (PMID 41155591, 2025). "FAPI-X radiopharmaceuticals target the over-expressed FAP in the tumoral stroma which, in some cases may account for as much as 90% of the entire tumour mass." (PMID 40069442, 2025). "However, FAP expression is elevated across various tumor types in the breast, colorectal, pancreatic, lung, bladder, ovarian, and other organ cancers." (PMID 40607439, 2025). "Tumor biopsies confirmed successful co-localization of MP0317 with FAP and CD40." (PMID 40700292, 2025). "Collectively, these data reinforce the hypothesis that FAP expression in the tumor stroma may enhance the likelihood of distant dissemination in ccRCC." (PMID 41303595, 2025). "Therefore, it seems feasible to construct molecular probes targeting FAP for direct tumor radionuclide diagnosis and therapy." (PMID 39839493, 2025). "Recently, radiotracers targeting fibroblast activation protein (FAP) have been developed on account of the FAP-specific inhibitor (FAPI), demonstrating excellent diagnostic performance and offering a novel form of pan-tumor tracing across various cancers." (PMID 39963103, 2025). "FAP-positive (FAP+) CAFs produce ECM proteins that contribute to migration of tumour cells." (PMID 39780187, 2025). "The interactions between SPP1+ macrophages and FAP+ fibroblasts could be a prospective point for anti-tumor progression and metastasis." (PMID 40438108, 2025). "Furthermore, FAP-modified, tumor-derived exosome-like vesicles (eNVs-FAP) demonstrated potent anticancer vaccine activity by inducing robust tumor-specific cytotoxic T lymphocyte (CTL) responses." (PMID 40191202, 2025). "FAP may contribute to aberrant tumor angiogenesis, leading to insufficient blood supply and the formation of hypoxic regions within the tumor, thus indirectly enhancing radiotherapy resistance." (PMID 40430845, 2025). "We have demonstrated the close distance between FAP+ fibroblasts and TAMs in tumor region of PCa." (PMID 40438108, 2025). "Our observations and others showing that eliminating FAP-positive CAFs in immunocompetent mouse models increased CD8+ tumor infiltrating lymphocytes suggest that FAP-targeted therapies represent a strategy for enhancing the immune anti-tumor response." (PMID 39868181, 2025). "Therefore, optimizing the FAPI molecular structure, enhancing tumor uptake and metabolic stability, and developing more efficient targeting FAP radiopharmaceuticals are essential for advancing this field." (PMID 40438601, 2025). "Adoptive transfer of chimeric antigen receptor (CAR)-T cells specifically designed to target FAP-expressing cells has shown promise in depleting FAP+ populations, including CAFs, thus limiting tumor stroma formation and enhancing the effectiveness of chemotherapeutic agents." (PMID 40313969, 2025). "OncoFAP is a highly specific ligand for FAP, offering broad tumor‐targeting capabilities." (PMID 40656546, 2025). "Eliminating CAFs may destabilize the tumor environment and promote metastasis, underscoring the need for further research on FAP-targeted therapies." (PMID 41373408, 2025). "We hypothesized that FAP/IL-15 CAR-T cells would specifically recognize and eliminate both FAP-positive tumor cells and CAFs, thereby disrupting stromal components essential for solid tumor progression." (PMID 41455698, 2025).
tumor (continued). "These 4-1BBL antibody fusion proteins provide signal 2 to 4-1BB-expressing T cells, either in cis by binding to CD19-expressing malignant B cells in combination with the CD20-TCB glofitamab or in trans by binding to FAP-expressing tumor fibroblasts in combination with the CEA-TCB cibisatamab." (PMID 41283511, 2025). "Therefore, in recent years, tumor assessment and treatments targeting FAP have been extensively studied and applied clinically, providing benefits to patients." (PMID 40607439, 2025). "BM-MSCs were induced by tumor cells to migrate, invade and to trans-differentiate in cancer associated fibroblasts (CAFs) as demonstrated by increased expression levels of α-SMA and FAP-α." (PMID 39930439, 2025). "Moreover, the [68Ga]Ga-AAZTA-FAPI-46 tracer uptake magnitude fully agrees with literature data on FAPI-46-based tracers that employed tumour models generated by FAP transfected cell lines." (PMID 40762892, 2025). "Notably, tumors such as pancreatic cancer, breast cancer, sarcomas, gastrointestinal cancers, and gynecological malignancies exhibit a high FAP expression in the tumor stroma, making them ideal candidates for FAPI-based imaging." (PMID 40283957, 2025). "All multimodal ligands demonstrated specific accumulation in the FAP-expressing tumor." (PMID 41258458, 2025). "However, after subcutaneous implantation into the mouse body after a certain period of time, a positive reaction to FAPα in tumor stromal tissues was shown by immunohistochemistry (IHC), probably due to the attraction of FAPα-positive stromal cells." (PMID 40918451, 2025). "FAP has gained attention as a novel target for tumor imaging." (PMID 40066225, 2025). "Therefore, the future direction would be to a combinatorial strategy, with FAP-RLT targeting the stiff stroma while other modalities targeting tumor themselves." (PMID 41425958, 2025). "sFAP may compete with tumor-bound FAP for radiopharmaceutical binding, potentially affecting their intended targeting specificity, distribution and clearance kinetics." (PMID 40000459, 2025). "Furthermore, in the most aggressive tumors in which these TME cells were abundant, we observed FAP + CAFs surrounding tumor cells (as previously reported with myCAFs in other solid tumors) as well as near CD8 + and CD68 + cells." (PMID 39751643, 2025). "Therefore, [68Ga]-Ga-FAPI, a novel radiotracer targeting FAP, was engineered to visualize tumor stroma." (PMID 39744055, 2025). "In oncology, PET radiopharmaceuticals based on FAP inhibitors (FAPI) have shown high tumor-to-background contrast, consistent with the observation that FAP-positive cancer-associated fibroblasts are present in the stroma of a vast majority of epithelial tumors." (PMID 41515504, 2025). "Furthermore, researchers have developed CAR-T cells targeting fibroblast activation protein (FAP), which is abundant in tumor stroma." (PMID 40382583, 2025). "In contrast, FAP is markedly overexpressed in the tumor stroma of more than 90% of epithelial cancers and is also upregulated in several chronic inflammatory conditions including hepatic fibrosis, cardiovascular pathologies, and autoimmune diseases like rheumatoid arthritis." (PMID 41155591, 2025). "FAP represents a promising target for tumor imaging and therapy." (PMID 40006089, 2025). "When BM-MSCs were grown in presence of FaDu and SCC-011 cells, they showed increased expression levels of alpha smooth muscle actin (α-SMA) and fibroblast activation protein alpha (FAP-α) indicating their transformation in tumor-educated BM-MSCs with features of CAFs." (PMID 39930439, 2025). "This suggests that FAP may indirectly influence radiotherapy efficacy by modulating the tumor microenvironment, potentially promoting angiogenesis and the formation of a hypoxic microenvironment." (PMID 40430845, 2025).
tumor (continued). "Moreover, since CAFs secrete tumor proliferative factors such as anti-alpha smooth muscle actin and fibroblast activation protein alpha (FAPα), and growth factor TGF-β, their levels were evaluated." (PMID 40430851, 2025). "Additionally, the clinical evaluation of 68Ga-FAPI-RGD, a PET probe simultaneously targeting fibroblast activation protein (FAP) and integrin αvβ3, has demonstrated higher tumor uptake and tumor-to-background ratio (TBR) compared to traditional 18F-FDG PET/CT." (PMID 39911388, 2025). "The combinational approach of co-targeting a tumor cell antigen (MAGEA4) and a CAF antigen (FAP) may enhance and broaden the anti-tumor immune response, potentially overcoming issues of tumor heterogeneity and antigen loss." (PMID 41345672, 2025). "Their FAP specificity and retention were evaluated in cellular and xenograft tumor models." (PMID 41258458, 2025). "Nevertheless, we also observed a trend toward higher percentages of these fibroblasts at the center of more aggressive tumors, in line with previous IHC studies that have suggested that FAP + CAFs play a key role not only at the tumor’s margin but also at its core." (PMID 39751643, 2025). "FAP-CAR T cells specifically target FAP-high CAFs, suppressing tumor growth." (PMID 40230452, 2025). "In addition, disialoganglioside 2 (GD2) and fibroblast activation protein (FAP) have been investigated as targets for immunocytokines in several tumor types." (PMID 41568361, 2025). "Interestingly, even when HT1080 hFAP accounted for only 10% of the initial culture, a significant amount of FAP was observed in the P+H (10:1) culturing experiments, thereby eventually indicating the formation of a “protective” layer for the tumor." (PMID 40704837, 2025). "highlighted a novel anti-stroma application, where synNotch drives CAR expression only in stromal cells expressing fibroblast activation protein (FAP), taking advantage of the abundant but tumor-restricted presence of FAP to activate T-cells in a tumor-specific but antigen-independent manner." (PMID 41584599, 2025). "Notably, SPP1+ macrophages interacted with FAP-positive CAFs, contributing to the establishment of a hypoxic tumor microenvironment, which is known to promote tumor progression and resistance to therapy." (PMID 40599798, 2025). "FAP+ CAFs, which are mainly located around tumor borders, also play a role in the TME." (PMID 40051497, 2025). "Targeting FAP to eliminate CAFs combined with chemotherapy drugs maybe an effective way to inhibit tumor growth." (PMID 40248695, 2025). "Targeting FAP could disrupt the tumor-promoting stroma and enhance immune infiltration and antigen presentation within the tumor." (PMID 41345672, 2025). "Interestingly, the presence of both FAP + CAFs, T-cyts (CD8 +), T-regs (CD4 + FOXP3 +), and macrophages (CD68 +) above P75 (log-rank p = 0.016) at the tumor center was associated with worse CSS." (PMID 39751643, 2025). "Overall, FAP + cells were the most abundant stromal cells in the tumor." (PMID 39751643, 2025). "[177Lu]Lu-FAP-2286 was well tolerated and demonstrated significant retained tumour uptake." (PMID 41049848, 2025). "Together, these approaches highlight the versatility of FAP as a tumor-specific target." (PMID 41441395, 2025). "Numerous studies have shown that α-SMA (+) FAP (+) CAFs play a role in promoting tumor progression." (PMID 40280913, 2025). "The druggability of PDPN, PRSS3, GREM1, and LGALS1, alongside the established relevance of FAP, provides multiple entry points for stromal-directed interventions that could complement tumor cell–targeted therapies." (PMID 41198614, 2025). "However, with an improved understanding of the tumour microenvironment, current research focuses on combination therapies to optimize FAP-targeted approaches, particularly involving the immune system." (PMID 40741380, 2025).
tumor (continued). "Recently, it has been reported that the interaction between SPP1+ Mac and FAP+ fibroblasts may promote the formation of demyelinated regions in the tumor microenvironment by remodeling the ECM." (PMID 40001138, 2025). "The FAP-mediated tumor microenvironment plays a key role in drug resistance of tumor cells." (PMID 40484962, 2025). "Antitumor effects have been demonstrated for fusion proteins composed of antibodies targeting different tumor-associated antigens (e.g., CEA, EDB, EDA, GD2, EGFR, FAP) and many cytokines of the common gamma chain receptor family (e.g., IL-2, IL-15, IL-15/IL15Rα, IL-21, IL-7)." (PMID 40370435, 2025). "The theranostic approach exemplified by [137La]La-FAP-2286 offers potential advantages for both tumour detection and treatment monitoring in FAP-expressing malignancies, though further characterisation of its binding affinity, pharmacokinetics, and therapeutic efficacy remains necessary." (PMID 40725089, 2025). "In FAP- and integrin-positive tumor models, both BRLs exhibited high tumor uptakes." (PMID 40869454, 2025). "High expression of FAP was related to higher levels of the tumor marker CA19‐9 (p = 0.012)." (PMID 41036616, 2025). "Furthermore, in these aggressive tumors, we observed FAP + stromal cells surrounding tumor cells and near CD8 + and CD68 + cells." (PMID 39751643, 2025). "This suggests that FAP expression in the tumor microenvironment may not only reflect stromal activation but could also be influenced by the presence of specific immune cell populations or cytokines that modulate fibroblast behavior." (PMID 41373408, 2025). "Subsequent studies also found that FAP CAR-T cells can inhibit tumor growth and improve outcomes." (PMID 40607439, 2025). "FAP promotes tumor angiogenesis by promoting neovascular sprouting and vascular co-option." (PMID 40438601, 2025). "Importantly, FAP also plays a significant role in immune modulation within the tumor microenvironment." (PMID 41373408, 2025). "Notably, FAP + CAFs and TILs displayed a pronounced presence at the tumor periphery, which suggests that they play different roles within the TME." (PMID 39751643, 2025). "This is particularly true in the tumor stroma, where FAP is commonly expressed on cancer-associated fibroblasts (CAFs), a major component of the tumor microenvironment; however, it is notably absent in normal fibroblasts." (PMID 41373408, 2025). "This suggests that FAP activation may not only foster tumor growth and survival but also mediate chemoresistance, highlighting its potential as a therapeutic target." (PMID 41373408, 2025). "FAP+SMA+ CAFs have been described to form extensive layers within the stromal regions or around tumor cell clusters in late-stage tumors, while MYH11+SMA+ CAFs were predominantly found in early-stage tumors, encircling clusters of cancer cells in a single layer." (PMID 39909044, 2025). "Fibroblast Activation Protein α (FAPα or FAP) is a cell-surface type II transmembrane glycoprotein overexpressed in the tumor microenvironment, specifically on the surface of cancer-associated fibroblasts (CAFs) and for some solid tumors on the tumor cell membrane as well." (PMID 40000459, 2025). "FAP expression in malignant tumors is predominantly expressed by cancer-related fibroblasts (CAFs), which are important regulators of tumor evolution, growth, angiogenesis, immunity, and invasive behaviors (invasion and metastasis) through direct cytokine and extracellular contacts and secretion." (PMID 40484962, 2025). "Furthermore, a fractionated therapy study, which involved FAP+ patient derived xenograft (PDX) tumor bearing animals was also completed." (PMID 40542914, 2025). "Notably, the crosstalk between SPP1+ macrophages and FAP+ CAFs was found to promote tumor progression." (PMID 41425545, 2025).